EGFR (epidermal growth factor receptor)
Diseases named in the same sentence as EGFR in open-access papers (continued):
Sharing a sentence is not in itself a finding about the gene and the disease.
invasive carcinoma (14 papers, 2007 to 2025). A carcinoma that is not confined to the epithelium, and has spread to the surrounding stroma. "The majority of DCIS cases expressing EGFR were CEIN related (9 of the 10 positive cases had associated invasive carcinoma), mostly high grade or intermediate grade, and almost all with comedonecrosis." (PMID 26657114, 2015). "EGFR, in particular, showed strong expression in invasive carcinoma samples, while TROP2 was expressed at moderate levels in the majority of samples." (PMID 40806559, 2025). "TIMER2.0 was used to identify the correlation between EGFR and other gene expressions in breast-invasive carcinoma subtypes with purity adjustments such as FGF2, FGFBP1, TGFA, TGFBR3, and IGF1R in all BRCA patients." (PMID 36430763, 2022). "Three DCIS and seven invasive carcinomas with normal EGFR expression underexpressed FHIT, which suggest that detection of FHIT expression could be of use either alone or with other markers such as EGFR, in identifying a subset of proliferative breast lesions with malignant potential." (PMID 17164758, 2007). "Among invasive carcinomas (N = 340), 214 (62.9%) were CK5/6-positive, 265 (77.9%) were CK14-positive, and 299 (87.9%) were EGFR-positive." (PMID 31788484, 2019). "Three DCIS and seven invasive carcinomas with normal EGFR expression underexpressed FHIT, whereas two DCIS and 11 invasive carcinomas with normal FHIT expression overexpressed EGFR." (PMID 17164758, 2007). "Although FHIT underexpression and EGFR overexpression followed a overall similar distribution in proliferative BBD lesions and in invasive carcinomas, they were not always concordant in individual cases." (PMID 17164758, 2007).
large cell neuroendocrine carcinoma (14 papers, 2013 to 2025). A usually aggressive carcinoma composed of large malignant cells which display neuroendocrine characteristics. "One survivor had a histological subtype of large cell neuroendocrine carcinoma and the other received targeted therapy for epidermal growth factor receptor mutation." (PMID 26237019, 2014). "Since we found in the literature a case of large cell neuroendocrine carcinoma of the lung harboring EGFR mutation responding to Gefinitib, EGFR status was evaluated by direct sequencing, resulting wild type." (PMID 23379295, 2013). "This article presents a rare case report of a patient with EGFR L861Q positive adenosquamous lung carcinoma who transformed into large cell neuroendocrine carcinoma following treatment with Almonertinib." (PMID 40040728, 2025). "We report a case of a 64-year-old Asian man with epidermal growth factor receptor T790M-positive adenocarcinoma that transformed to epidermal growth factor receptor T790M-negative large-cell neuroendocrine carcinoma after osimertinib therapy." (PMID 32762742, 2020). "Case 3 had a large cell neuroendocrine carcinoma, an aggressive form of NSCLC, and responded to aggressive combined modality therapy; case 2 responded to targeted therapy for EGFR mutation." (PMID 26237019, 2014). "EGFR was positive in 40 cases (64.5%) of including 33 cases (71.7%) of NSCLC compared to 5 cases (35.7 %) of SCLC, in addition to 2 cases of large cell neuroendocrine carcinoma (p=0.014)." (PMID 34181347, 2021).
leukoplakia (14 papers, 2012 to 2024). A white patch or plaque on a mucous membrane that cannot be characterized clinically or pathologically as any other disease. "Numerous studies have shown that leukoplakia often exhibits overexpression of EGFR, which correlates with a higher risk of malignant transformation." (PMID 39676869, 2024). "The increased expression of EGFR in OPMD such as leukoplakia and OSMF favors EGFR as a valuable diagnostic marker." (PMID 36010285, 2022). "Thisstudy evaluated the quantitative expression of EGFR in normal oral mucosa, oral leukoplakia and oral submucous fibrosis to predict the malignant risk in compliance with the intensity of staining with EGFR." (PMID 26697149, 2015). "EGFR expression was associated with clinical and pathological features.Results: EGFR was positive in 62.5% of the leukoplakias and 50% of normal oral epithelium." (PMID 22322523, 2012). "There were differences in EGFR expression between leukoplakias in high and low-risk sites, with a higher number of EGFR positive lesions in high-risk than low-risk areas." (PMID 22322523, 2012). "In this study, we evaluated the influence of clinicopathological factors on the immunoexpression of EGFR in a group of oral leukoplakias as well as the association of EGFR and cellular proliferation." (PMID 22322523, 2012). "The association of p27 with EGFR warrants additional investigation, and, in the future, may allow for new treatment options for severe leukoplakias through EGFR inhibitors." (PMID 22322523, 2012). "Ries reached similar conclusions when studying the malignant transformation of 98 leukoplakias, particularly emphasizing that expression of EGFR correlated more strongly with malignant transformation in relation to the degree of dysplasia." (PMID 36982894, 2023). "EGFR was found to be overexpressed in leukoplakia and oral submucous fibrosis, thus suggesting a valuable diagnostic marker for early malignancy." (PMID 36010285, 2022). "The aim of the present study was to evaluate the expression of EGFR in habit induced oral leukoplakia and oral submucous fibrosis patients." (PMID 26697149, 2015). "Increased EGFR-DNA copy number has been associated with OSCC development in patients having a precursor, same-site leukoplakia, which also over-expressed EGFR." (PMID 24403051, 2014). "EGFR was positive in 30 (62.5%) cases of leukoplakia, and staining was localized to membranes and involved a basal extension to the suprabasal layers." (PMID 22322523, 2012). "In conclusion EGFR expression is frequent in oral leukoplakia, especially in those lesions located on floor of the mouth and on the tongue." (PMID 22322523, 2012). "Studies also reveal the upregulation of COX-2 and EGFR in oral leukoplakia and oral carcinogenesis." (PMID 26919242, 2016). "EGFR inhibitors may thus be potentially useful in preventing malignant transformation of such leukoplakia lesions." (PMID 24403051, 2014). "The expression of EGFR in leukoplakias is likely altered by clinicopathological features and may modulate proliferation indexes." (PMID 22322523, 2012). "Previous studies have demonstrated increased EGFR expression in oral leukoplakias." (PMID 22322523, 2012). "Key words:Oral leukoplakia, EGFR, p27, Ki-67, epithelial dysplasia." (PMID 22322523, 2012).
leukoplakia (continued). "Studies evaluating the expression of EGFR in OSCC and leukoplakia have shown a significant correlation in OSCC, when compared to leukoplakia." (PMID 36010285, 2022). "EGFR expression is related to disease progression from nonmalignant leukoplakia to invasive disease." (PMID 36008552, 2022). "When leukoplakia slides were analyzed, expression of EGFR was not restricted to cell membrane of basal and parabasal layer but it was observed in various layers of the epithelium." (PMID 26697149, 2015). "EGFR was expressed in leukoplakia regardless of grade of dysplasia, where positive staining was seen in all the cases of OL with histologically proven dysplasia, irrespective of its grading." (PMID 26697149, 2015). "Tobacco smoking is the strongest independent risk factor for leukoplakia, and studies show that there is a clear dose-dependent relationship for cigarettes Interestingly; EGFR expression did not vary in leukoplakias from smokers and non-smokers." (PMID 22322523, 2012). "When all epithelial layers were considered, p27 indexes were also significantly different between EGFR positive and negative leukoplakias." (PMID 22322523, 2012). "A reduction in the expression of p27 in oral leukoplakia in comparison with normal oral epithelium has been described in previous studies but the role of EGFR in this reduction has not been explored yet." (PMID 22322523, 2012).
metastatic prostate carcinoma (14 papers, 2005 to 2025). A carcinoma that arises from the prostate gland and has spread to other anatomic sites. "More recently, mir-135a-1 was identified as an inhibitor of multiple oncogenic pathways (including EGFR) acting as a tumor suppressor in metastatic prostate cancer both in vitro and in vivo." (PMID 34948154, 2021). "Some studies showed that EGFR was predominantly expressed in hormone-refractory and metastatic prostate cancer." (PMID 31998647, 2019). "The ability of Cetrorelix to downregulate EGFR signalling and subsequently reverse the antiadhesiveness found in metastatic prostate cancer highlights a novel potential target for therapeutic strategies." (PMID 15655536, 2005). "To check if the isolated fractions represent tumoral subpopulations with differential phenotypes we performed gene expression analysis by RT-qPCR of CTCs isolated from patients with prostate metastatic cancer (n = 8; 26 ± 19.79 x 106 PBMCs) using anti-EpCAM, anti-EGFR and anti-FGFR magnetic beads." (PMID 27711186, 2016). "EGFR siRNA increased the subG1 population in transfected metastatic prostate cancer cells." (PMID 23531874, 2013). "We have previously reported the prognostic value of detection of EGFR and ARV7 in hormone-sensitive metastatic prostate cancer, in a patient cohort partly overlapping the present study." (PMID 31877738, 2019). "Combination of docetaxel with CYA and epidermal growth factor receptor (EGFR) inhibitor gefitinib induced greater antiproliferative and apoptotic effects on SP cell fractions isolated from metastatic prostate cancer cells than individual drugs." (PMID 22768203, 2012). "We have recently demonstrated that adding EGFR-inhibitor lapatinib can enhance the effectiveness of PTX in inducing apoptosis in a paclitaxel-resistant, androgen-independent metastatic prostate cancer cells line DU145-TXR, both in vitro as well as in xenograft tumors." (PMID 22768203, 2012). "The positive expression of EGFR and COX-2 in non-metastatic and metastatic prostate cancer." (PMID 24155892, 2013).
neurofibroma (14 papers, 2008 to 2024). An intraneural or extraneural neoplasm arising from nerve tissues and neural sheaths. "FACS analysis (of cells from three additional neurofibroma tumors) showed that on average p75+/EGFR+/P2ry14- cells formed spheres at a frequency of 23.4%, while 64.8% of p75+/EGFR+/P2ry14+ cells formed spheres." (PMID 35311647, 2022). "Together, these studies suggest the presence of progenitor-like cells in neurofibromas, which depend on EGFR for self-renewal." (PMID 35311647, 2022). "A transgenic mouse model with EGFR overexpression in Schwann cells elicited features of neurofibromas such as hyperplasia, excess collagen, mast cell accumulation, and progressive dissociation of non-myelin-forming Schwann cells from axons." (PMID 23319880, 2012). "Both PTEN and EGFR levels in purified Schwann cells taken from human peripheral nerve and neurofibroma cells; transformed cells taken from MPNST cell lines and solid tumors at various stages of disease were analyzed by microarray gene expression analysis." (PMID 23319880, 2012). "The idea that these cells may be tumor-initiating cells is consistent with the finding that human neurofibromas sorted for co-expression of the SC marker p75+ and EGFR show limited self-renewal in vitro." (PMID 35311647, 2022). "EGFR+ cells that co-express the SC marker S100 account for about 1.8% human neurofibroma cells." (PMID 35311647, 2022). "Notably, while neurofibromas rarely form, elevation of EGFR in WT SCPs and SCs is sufficient to mimic this nerve disruption phenotype." (PMID 35311647, 2022). "Also, EGFR-dependent Nf1-/- SCPs show increased self-renewal and form neurofibromas upon transplantation." (PMID 35311647, 2022). "Variants in promoter and UTR regions might also have a potential as phenotype modifiers, since animal models have already shown that high levels of EGFR expression modify the initiation of neurofibromas, increasing their numbers." (PMID 32858845, 2020). "Based on the notion that the Schwann cell growth factor neuregulin-1 and its receptor EGFR are expressed in neurofibroma and MPNST, mice models overexpressing neuregulin-1 or EGFR were developed." (PMID 34445326, 2021). "Analysis of microarray data from cell lines and bulk tumors isolated from human neurofibromas and MPNSTs indicate that there is a selective pressure to lose PTEN expression, while EGFR expression is induced during disease progression." (PMID 23319880, 2012). "Overexpressing EGFR in Nf1 wild-type Schwann cells leads to neurofibroma formation, although to a low penetrance, but not to MPNST." (PMID 34445326, 2021). "In addition, targeted therapy of EGFR/ErbB2 inhibits ErbB2 phosphorylation and Survivin upregulation, as well as downstream ERK1/2 and AKT activation, thereby reducing neurofibroma cell proliferation, which is consistent with our results of Survivin downregulation." (PMID 39346787, 2024).
neurofibroma (continued). "EGFR is abundantly expressed in neurofibroma and MPNST cell lines, although unfortunately the EGFR inhibitor erlotinib failed to inhibit tumor growth in Phase 2 trials of patients with advanced-stage MPNST166." (PMID 37081086, 2023).
pituitary adenomas (14 papers, 2008 to 2025). "Furthermore, ADAM12 overexpression is associated with tumor invasion in pituitary adenoma via the EGFR/ERK signaling pathway." (PMID 31796052, 2019). "A comprehensive study determined the presence of EGFR at the protein and mRNA levels in different pituitary adenomas." (PMID 38862897, 2024). "This study examined the expression levels of EGFR and its downstream signaling molecules in fifty-two sporadic pituitary adenoma specimens and six normal pituitary glands." (PMID 37446128, 2023). "The study entitled “The expression and prognostic significance of EG-VEGF in pituitary adenomas” demonstrated for the first time the correlation between EG-VEGF and EGFR in pituitary adenomas such as the compact acidophilic pituitary adenomas." (PMID 28386275, 2017). "Compact pituitary adenomas with acidophilic cells present an increased expression of EG-VEGF correlated with an overexpression of EGFR." (PMID 28386275, 2017). "These mutations seem to affect the recycling speed of the epidermal growth factor receptor (EGFR) to the membrane of the ACTH-secreting pituitary adenoma cells, thus prolonging its effects." (PMID 28005997, 2016). "Indeed, EGFR is expressed in ACTH-secreting pituitary adenomas in both species, and its inhibition with the EGFR inhibitor gefitinib has been shown to reduce POMC expression, subsequent ACTH production, and corticotroph cell proliferation." (PMID 40943544, 2025). "Interestingly, subsequent studies also indicated that ADAM12 induced EMT in pituitary adenomas through the EGFR/ERK signaling pathway and promoted cell migration, invasion, and proliferation." (PMID 34604068, 2021). "Moreover, studies have shown that pituitary adenomas with mutated USP8 display an increased incidence of EGFR expression, EGFR protein abundance and the mRNA expression levels of POMC, indicating that EGFR plays an important role in adenomaigenesis." (PMID 31798535, 2019). "In summary, IL‐6, CCL2, EGF/EGFR, VEGF/VEGFR, and other cytokines are expressed in pituitary adenomas and are generally related to their aggressiveness, occurrence, and development." (PMID 38738958, 2024). "EGFR expression was observed by 2.5 months in transgenic (Tg) mice; and aggressive ACTH-secreting pituitary adenomas with features of Crooke’s cells developed by 8 months with 65% penetrance observed." (PMID 38862897, 2024). "S100 proteins have been shown to be expressed in pituitary adenomas in a manner that correlates with VEGF and EGFR expression." (PMID 31040912, 2019). "Studies have confirmed that EFGR was overexpressed in recurrent growth hormone‐secreting pituitary adenomas and invasive silent subtype III adenomas, suggesting that EGF/EGFR expression may be related to the recurrence and aggressiveness of pituitary adenomas." (PMID 38738958, 2024). "EGFR expression is more common in the hormonally active pituitary adenomas than in the non-functioning ones." (PMID 37446128, 2023). "The lack of correlation between EG-VEGF and EGFR in papillary-type pituitary adenomas could be explained through the different molecular profiles of pituitary adenomas." (PMID 28386275, 2017).